RNU6-448P (RNA, U6 small nuclear 448, pseudogene)
Gene: Small nuclear RNA gene on chromosome 5 (84,196,883 to 84,196,989, forward strand). Ensembl gene ENSG00000252861.
Homologues: Orthologues: chimpanzee U6 (100% identical), macaque U6 (89% identical), guinea pig U6 (65% identical), dog U6 (62% identical). Paralogues in human: RNU6-1316P (73% identical), RNU6-196P (73% identical), RNU6-428P (73% identical), RNU6-144P (72% identical), RNU6-14P (72% identical), RNU6-16P (72% identical), RNU6-183P (72% identical), RNU6-35P (72% identical), RNU6-46P (72% identical), RNU6-1159P (71% identical), RNU6-1179P (71% identical), RNU6-1311P (71% identical), and 1282 more.